IL10 (interleukin 10)
Diseases named in the same sentence as IL10 in open-access papers (continued):
Sharing a sentence is not in itself a finding about the gene and the disease.
tumor (continued). "There is discordance whether thymus-derived Tregs mediate the conversion of conventional CD4 T cells to immunosuppressive Tregs by TGF-β and IL-10 or if peripherally-derived Tregs are accumulating in the tumor tissue." (PMID 29032503, 2018). "We found that components of the antigen processing pathway (H2-K1, β2 m) were elevated in A9 metastatic tumours expressing IL-33, whereas the expression of immunosuppressive factors (IL-10, Ptgs2) were diminished, thereby altering the tumour microenvironment toward immune responsiveness." (PMID 29440650, 2018). "First, the TIGIT interaction with PVR is of a much higher affinity compared to the TIGIT interaction with CD112, participating in the negative regulation of activated T cells and NK cells by up-regulating IL-10 expression and down-regulating IL-12 expression in tumor cells or APCs." (PMID 29735917, 2018). "Besides promoting Treg function, CD163+ TAMs (M1-like) located around tumor/connective tissue also strongly secrete IL-10 and express more PD-L1 compared to other TAM subsets found within the tumor." (PMID 30619850, 2018). "In addition, in tumor tissue, IL-10 was found to be upregulated by calcitriol and its analogs during the early stages of tumor growth." (PMID 30037009, 2018). "In MC-38 tumor models, we demonstrated that TgMGLL stimulated the expression of proinflammatory cytokines (IL-1β and TNFα) and reduced the levels of anti-inflammatory cytokines (IL-10, Arg-1, and TGFβ) in a CB2-dependent manner in TAMs." (PMID 29968710, 2018). "However, in some studies ablating IL-10 was associated with an increased level of MDSCs and Tregs in TME and in the tumor-draining lymph nodes." (PMID 30233579, 2018). "Moreover, combined silencing of PD-L1 and IL-10 in DC vaccination showed even stronger induction of anti-tumor responses in vitro and in vivo indicating the potential of combining DC modifications in maximizing anti-tumor responses." (PMID 29867960, 2018). "On the opposite, M2 macrophages play a significant role in tumor progression, promote tissue repair and angiogenesis, and are characterized by the production of immuno-suppressive factors such as IL10, Arginase, IDO and TGF-β, which inhibit cytotoxic CD8+ T cell-mediated immune response in the TME." (PMID 29545811, 2018). "Overall, these results suggest that type I IFN plays a dual role on DC-mediated tumor immunity, by promoting the generation of antitumor responses, but at the same time inducing regulatory mechanisms -including IL-10- to balance the magnitude of these responses." (PMID 30233565, 2018). "Tumor-derived exogenous TGF-β may have a greater impact on Tregs because IL-10 can only induce T-cell differentiation into Tregs, whereas TGF-β can promote Tregs proliferation in addition to inducing differentiation." (PMID 30477520, 2018). "Tie2-expressing macrophages are known to secrete IL-10, and thus may contribute to the increased ratio of M2 to M1 macrophages in the tumor microenvironment." (PMID 29382395, 2018). "The CSCs and the Cancer cells induce the production of immune-modulatory molecules such as IL-10, IL-13 and TGF-β that are conducive to the proliferation of the M2-Tumor Associated Macrophages (M2-TAM), the Type II T-helper (TH2) cells and the T-regulatory (Treg) cells." (PMID 30183728, 2018). "Also increased in TiME-II tumors were neutrophils, conventional DCs (cDC), cancer-associated fibroblasts (CAF), and tumor-associated macrophages (TAM) with high PD-L1, which were associated with greater IL-10 production and phosphorylation of Akt and NF-κβ." (PMID 29618661, 2018). "Indeed, cancer cell-derived cytokines, such as transforming growth factor β (TGFβ) and interleukin (IL)-10, frequently skew the differentiation of tumor-infiltrating immune cells into a tumor-promoting phenotype." (PMID 30355585, 2018). "Thus, although different IL-10 sources coexist in the tumor setting, DC-derived IL-10 seems to determine vaccination efficacy." (PMID 30233565, 2018).
tumor (continued). "On day 21, granulocyte-colony stimulating factor (G-CSF), granulocyte-macrophage (GM)-CSF, IL-4, IL-6, and IL-10 were found to be increased by calcitriol and its analogs, whereas on day 33, their level was found to be decreased as compared with control tumor-bearing mice." (PMID 30037009, 2018). "IL-10 is essential to suppress tumour promoting inflammation mediators; however, IL-10 might play a potential role in regulating tumour angiogenesis." (PMID 29256156, 2018). "Our results suggest that IL-10 may impact a diminished M1 macrophage number in the tumor microenvironment." (PMID 29361917, 2018). "According to some authors IL-10 plays a dual role in the tumor microenvironment." (PMID 29849947, 2018). "The authors found that miR-145 secreted by colorectal cancer cells via MVs is taken up by TAMs, targets histone deacetylase 11 (HDAC11) and TLR4, enhances the production of IL-10, promotes the polarization of TAMs to M2-like macrophages, and promotes tumor progression." (PMID 30443251, 2018). "Nonetheless, immunosuppression of the DCs by factors like IL-10, TGF-β, PD-1, and IDO is ignored in many studies, including the TriMix trial, and may cause substantial downregulation of the anti-tumor response." (PMID 29867960, 2018). "Compared to the macrophages in WT group samples, the macrophages isolated from PKN2-WT tumor showed significantly higher expression of Il1b, Tnf, Cxcl9, Il23, Ros1 and Il12b and significantly lower expression of Tgfb1, Vegfa, Egf, Retnla and Il10, illustrating predominant M1 phenotype." (PMID 29368606, 2018). "Moreover, it has been shown that IGFs enhance the secretion of IL-10 in bone marrow monocyte-derived DCs, thereby enhancing the immunosuppressive status of the tumor environment." (PMID 29922232, 2018). "CD200fc injection enhanced the tumor-induced IFN-g response while suppressing the IL-10 response." (PMID 29721190, 2018). "However, the IL-10, involved in the tumor-induced immunosuppression, was found to be increased after treatment with calcitriol and its analogs." (PMID 30037009, 2018). "Moreover, MDSCs produce a substantial amount of IL-10, which allows to form an immunosuppressive in vivo niche, implying the critical role of IL-10 for development of a tumor-permissive TME." (PMID 28929459, 2018). "Moreover, LCs in the CIN lesions did not express adhesion/costimulation molecules for T cell activation, suggesting that the aberrant expressions of TNF-α and IL-10 played a role in inhibiting the anti-tumor functions of LCs." (PMID 30477198, 2018). "An important implication of our findings that healthy individuals have an IL-10-mediated immune response toward recoverin is that expression of recoverin by malignant cells may contribute to enhanced immune regulation in the tumor microenvironment." (PMID 30271775, 2018). "Moreover, B-cell infiltrates regulate tumor process through productions of antibodies and interleukin-10." (PMID 29568299, 2018). "High tumor IL-10 expression can be used as a predictor of tumor stage." (PMID 30517305, 2018). "In malignant diseases, PD-1 ligands become upregulated on leukocytes in the tumor microenvironment by various pro-inflammatory cytokines, e.g. interferon γ, interleukin 10, and tumor necrosis factor α, produced by tumor cells and other leukocytes such as T cells." (PMID 30261066, 2018). "Subsequently, the recruited monocytes transform into TAMs stimulated by cell factors (like macrophage colony-stimulating factor (M-CSF), vascular permeability factor (VEGF)-1, IL-4, IL-10, IL-13), and then, tumor angiogenesis is induced by TAM-secreted angiogenesis factors." (PMID 29458367, 2018). "Alternatively, IL-4 and IL-13 produced by Th2 cells induce macrophage polarization towards the M2 phenotype; M2 macrophages secretes anti-inflammatory cytokines such as IL-10, immunosuppressive factors, and tumor growth factors, which promote tumor cell growth and metastasis." (PMID 29707119, 2018).
tumor (continued). "Notably, DCs in TME that is free of IL-10 are able to restore their functionality and can effectively process and present tumor antigens released from dying tumor cells." (PMID 29954431, 2018). "In addition to direct killing of cytotoxic cells and modulation of other immune cells, Treg cells secrete immunomodulatory cytokines, in particular TGF-β and IL-10, to directly affect tumor cells." (PMID 30319662, 2018). "IL-10 is a potent inhibitor of both the alveolar macrophages and NK-cell anti-tumor activities." (PMID 29732034, 2018). "It is known that the anti-inflammatory cytokines IL-10 and IL-4 are involved in the maintenance of Th2 response profile that, with consequent suppression of the Th1 response, produces a microenvironment favorable to tumor growth." (PMID 30200386, 2018). "IL-10-producing cells play a crucial role in tumour development." (PMID 29614988, 2018). "Similarly, Tregs promote tumor progression in a number of ways, including inhibiting the activation and survival of T-cells and increasing levels of IL-10 and TGF-β29–31." (PMID 29440769, 2018). "Notably, the experimental groups in the current study that exhibited significant reduction in tumor incidence displayed lower expression of IL-10 in spleen at 21 dpi." (PMID 30401976, 2018). "In addition, a previous study showed that carnosol has anti-tumor capacity through prevention of Treg cell differentiation, decreasing IL-4 and IL-10 production, and enhancing IFN-γ secretion in tumor-associated lymphocyte populations." (PMID 30150982, 2018). "Moreover, a clinical isolate CCR20 strain (a pks-positive E. coli obtained from human CRC samples) induced cellular senescence and increased tumor burden in AOM-treated IL-10(-/-) mouse models." (PMID 30413188, 2018). "However, excessive amounts of soluble factors secreted in a tumor microenvironment (TME) e.g. TGF-β, IL-10 or VEGF reduce the effectiveness of the applied treatment and cause further tumor progression." (PMID 29954431, 2018). "Summarizing, blocking of IL-10 in TME can have positive effects on tumor progression." (PMID 29954431, 2018). "Moreover, MDSCs have the ability to release important cytokines, to name a few, the TGF-β and IL10, among others, inside solid tumors, acting as immunosuppressants and promoting tumor growth." (PMID 30123112, 2018). "The adopt transfer of wide type or IL-10−/− B cells both restored tumor growth and reduced survival relative to BCDM, which suggested that IL-10 secretion may be not necessary in restoring tumor growth in murine models." (PMID 29568299, 2018). "Finally, the activation to the M2c phenotype is triggered by the exposure to anti-inflammatory cytokines secreted for instance by tumor cells, such as IL-10, TGF-β, and glucocorticoids." (PMID 29389898, 2018). "An examination of serum IL-10 levels revealed a significant difference between the control group and the observation group, suggesting that IL-10 is an important negative regulator of the tumor immune microenvironment and can promote tumor growth and metastasis." (PMID 30517305, 2018). "In addition, downregulation of IL-10 and IL-18 by HVT and/or ECpG treatment appears to be linked to defense against MDV infection as demonstrated by the significant reduction of tumor formation and MDV load in feathers." (PMID 30401976, 2018). "However, as IL-10 is produced not only by Tregs but also by myeloid cells that infiltrate the MC38 tumor, the application of shIL10–3 LVs targeting mainly myeloid cells is of great importance." (PMID 29954431, 2018). "The suppressive effect of B cells in the tumor setting was partly relied on IL-10 secretion." (PMID 29568299, 2018). "Myeloid-derived suppressor cells (MDSCs) inhibit anti-tumor immune function by stimulating the activity of immunosuppressive Tregs, producing reactive oxygen species (ROS) and by secreting anti-inflammatory cytokines like IL-10 and TGF-β." (PMID 30420856, 2018).
tumor (continued). "In addition, neutralization of ST2Lsignificantly decreased Treg cells and ST2L+Treg both in spleen and in tumortissue of tumor-bearing mice (Figure 5Eand F) and inhibited the protein levels of IL-4, IL-10, and IL-13." (PMID 29950152, 2018). "The mRNA levels of IL4 and IL10 in tumor cells separated from different xenografts were detected." (PMID 29368606, 2018). "Moreover, the expression of TAM associated genes such as CD33, CD16, IL6R, IL10, and FCGR3 enabled identification of a subgroup of patients with a poor outcome based upon tumor classification scores for predicting progression-free survival (PFS)." (PMID 29682521, 2018). "Mφ and tumor in situ can secrete IL-10 to recruit Tregs to tumor site indicating that Mφ may affect the number of FOXP3+ Tregs by cytokines." (PMID 28029650, 2017). "Moreover, pDCs in the tumor microenvironment trigger IL-5/IL-13-secreting Th2 cells and IL-10-secreting Tregs through the expression of OX40L and ICOSL." (PMID 29085361, 2017). "Given the significant association of serum IL-10 with overall survival in patients with AITL, we analyzed the infiltration of tumor-associated macrophages in tumor tissue of 21 AITL patients who had archived paraffin-embedded tissue blocks available for immunohistochemical staining." (PMID 29100307, 2017). "Interleukin-10 (IL-10) has both immunosuppressive and antiangiogenic effects and may therefore exert both tumour-promoting and antitumour effects." (PMID 28280748, 2017). "On contrary, there are evidences suggesting that B-cell depletion could therapeutically enhance anti-tumor immune responses by decreasing IL-10 production from B cells." (PMID 28805741, 2017). "Moreover, TGF-β and IL-10, often considered as immune suppressive cytokines and present in the tumor micro-environment, induce IgA and IgG4 switching." (PMID 28785261, 2017). "Thus, we tested the levels of TGF-β1 and IL-10 in the supernatants collected from paired tumor and non-tumor primary renal cultures by ELISA." (PMID 28384121, 2017). "Moreover, IL-10 is also thought to promote tumor immune escape by diminishing anti-tumor immune response in the tumor microenvironment." (PMID 29029504, 2017). "GC cells themselves can also secrete IL-10, which may explain its reduction in GC patients after surgical removal of their tumor." (PMID 28558708, 2017). "IL-10 is one of the main tumor-suppression factors which produced by most of cancers." (PMID 28234961, 2017). "Finally, IL-10, an important immune inhibitory factor, was increased in tumor-bearing mice, but decreased in the hippocampus of mice without tumors treated with radiation only." (PMID 27893434, 2017). "To address this, following tumor inoculation we measured global cytokine mRNA differences, including TGFβ, TNFα, IL-10 and IFNγ, between WTTU and L3TU groups on day 5, the time point where we observed the greatest differences in cellular accumulation and CD69 positivity." (PMID 29109732, 2017). "In addition, pDCs exposed to tumor-derived factors would enhance IL-10 production by CD4+ Tregs through upregulation of ICOSL." (PMID 29085361, 2017). "IL-10 can also expand CD8+ tumor- infiltrating lymphocytes, promoting their killing activity." (PMID 28854209, 2017). "Moreover, STAT3 is a critical maintainer of cancer stem-like cells (CSC), and M2-like TAMs secret activators of STAT3 such as oncostatin M and IL10 to promote tumor cell activation and proliferation via interaction between TAMs and tumor cells." (PMID 28467800, 2017). "IL-10 is secreted by HRS cells in HL and also by tumor cells and associated macrophages in BL36." (PMID 28883511, 2017). "This leads to low level expression of tumour antigens and enhances other mechanisms of immunosuppression by development of T -cell tolerance to the tumour antigen and immunosuppressive cytokines such as IL-10, TGF-Beta or Tregs (Regulatory T cells)." (PMID 28275390, 2017). "Analysis of IL-10+ cells inside the tumor showed that most populations produced IL-10." (PMID 27926522, 2017).
tumor (continued). "Binding of IL-6, IL-10, and IL-17 to their receptors promotes the activation of JAKs; however, the anti-tumor immunomodulatory role of IL-6, IL-10 and IL-17 remains unclear and appears contradictory in some aspects." (PMID 29262601, 2017). "Tumour-associated macrophages reduce antimicrobial and antitumour activity by expressing low levels of MHA Class11, increase angiogenic mediators such as VEGF and COX2 derived PGE2 and IL-10 anti-inflammatory cytokine." (PMID 28275390, 2017). "In mouse models of breast cancer, macrophages contribute to tumor progression through a variety of mechanisms including IL-10 and arginase 1 (Arg1)-mediated immunosuppression, MMP 7/9 and CCL18-induced matrix remodeling, and EGF and TNFα-stimulated tumor cell migration and metastasis." (PMID 28881599, 2017). "In line with the growing Th2-bias and malignant T cell expression of factors such as PGE2, IL-10, and high-mobility group BOX-1 protein (HMGB1), the infiltration of mast cells, eosinophils, and tumor-associated macrophages (TAMs) with an M2 phenotype, typically increases during CTCL progression." (PMID 27717961, 2017). "However, Imiquimod, besides inducing IL-10, led to the highest percentages of PD-L1+ cells, a result also observed after vaccination of naive tumor-free mice." (PMID 27926522, 2017). "In addition, Tregs recruitment is increased in HO-1-dependent manner in 4T1 breast cancer and in tumor-bearing mice and HO-1 expression in cancer cells is related to the increased generation of IL-10 responsible for keeping DC immaturity." (PMID 28475131, 2017). "As in tumor-free mice, DC and monocytes showed the highest proportion of IL-10+ cells." (PMID 27926522, 2017). "This is blocked by tumor cell-derived cytokines such as IL-10 and TGFβ." (PMID 29156566, 2017). "TAMs are typically associated with an M2-like polarization state caused by tumour-derived lactic acid or secretion of immunosuppressive cytokines such as IL-4, IL-10, and IL-13 from different cells in the tumour microenvironment or B cell-derived immunoglobulins." (PMID 28210073, 2017). "Instead, given their higher expression of Il-10 and Tgfβ1, a more rational approach might be to add immune modulators to bolster our current combination therapy by further reducing tumor immunosuppression." (PMID 28539588, 2017). "The tumor promoting arm of that balance is determined by the presence of cells of myeloid origin, Type 2 suppressive T-cells (Tregs) and Th2-cells and IL-4, IL-6, IL-10 and IL-13 are relevant cytokines." (PMID 28402937, 2017). "Moreover, IL-10 is elevated in cancer and is thought to contribute to tumour growth and immune tolerance." (PMID 28099146, 2017). "This phenomenon is not incomprehensible, because M1 macrophages could be induced into M2 macrophages by some tumor derived cytokines such as CSF-1, IL10 and TGF-β." (PMID 29152078, 2017). "According to the cancer immunoediting theory inhibition of the protective functions of the immune system via overproduction of immunosuppressive cytokines, such as IL-10, may also facilitate tumor escape." (PMID 28286647, 2017). "Crosstalk between TAMs and tumor cells through anti-inflammatory cytokines such as interleukin-10 contributes to various aspects of tumor progression by activities such as promoting tumor angiogenesis, supporting destruction of basal extracellular matrix, and facilitating metastasis." (PMID 29362559, 2017). "IL10 knockout mice showed weakened tumor immune surveillance." (PMID 28594935, 2017). "We previously reported that JC-001 down-regulates systemic Th17-mediated immunity in both Hepa 1-6 and LLC1 immunocompetent tumor models and up-regulates IL-10 secretion and down-regulates IL-17A in conditioned medium from co-cultured tumor cells and splenocytes." (PMID 28399860, 2017).